SOX5 (SRY-box transcription factor 5)
Diseases named in the same sentence as SOX5 in open-access papers (continued):
Sharing a sentence is not in itself a finding about the gene and the disease.
bladder cancer (11 papers, 2019 to 2025). "In bladder cancer, SOX5 expression is up-regulated in bladder cancer tissues and in vitro cell lines." (PMID 38835366, 2024). "Specifically, LINC00839 regulates SOX5 either directly or indirectly through the miR-142 axis, which increases the resistance of bladder cancer cells to gemcitabine by promoting autophagy." (PMID 39628486, 2024). "The down-regulation of NAT10 results in the reduction of ac4C modification in specific regions of mRNA, impairing translational efficiency of BCL9L, SOX4, AKT1 as well as the stability of BCL9R and SOX5, thereby reducing bladder cancer burden." (PMID 38233839, 2024). "Prior evidence has documented that the modulation of the miR-132/Sox5 signaling pathway by circDOCK1 affects the migration potential of bladder cancer cells." (PMID 35031788, 2022). "However, circDOCK1 knockdown significantly suppressed bladder cancer cell proliferation, migration, and invasion by interfering with the circDOCK1/hsa-miR-132-3p/Sox5 pathway." (PMID 39967686, 2025). "In addition, in bladder carcinoma, circDOCK1 was identified to promote tumor progression by modulating the circDOCK1/hsa-miR-132-3p/Sox5 signaling axis." (PMID 34876132, 2021). "Highly expressed SOX5 can promote the expression of DNMT1 and inhibit the expression of p21 through DNA methylation, thus promoting cell growth and migration, while knockdown of Sox5 can inhibit the cell growth and migration of bladder cancer cells." (PMID 38835366, 2024).
Lamb-Shaffer syndrome (10 papers, 2017 to 2026). "Lamb-Shaffer syndrome (OMIM 616803) is attributed to variants in the SOX5 gene, following an autosomal dominant inheritance pattern." (PMID 39905544, 2025). "SOX5 is linked to Lamb-Shaffer Syndrome, which can cause an abnormal craniofacial phenotype including a facial asymmetry, depressed and/or broad nasal bridge, and bulbous nasal tip." (PMID 30631343, 2018). "The SOX5 gene has been identified as the pathogenic gene responsible for Lamb-Shaffer syndrome." (PMID 39905544, 2025). "Moreover, given the fact that SOX5 heterozygous inactivating variants cause neurodevelopmental disorders in humans (Lamb-Shaffer Syndrome; OMIM # 616803), our findings will also help to understand the episodic and social memory deficits described in those patients." (PMID 40720543, 2025). "Lamb-Shaffer syndrome (LAMSHF, MIM 616,803) is a neurodevelopmental disorder caused by genetic alterations due to haploinsufficiency of the SOX5 gene (SRY-related high-mobility-group box5, MIM 604,975)." (PMID 36759900, 2023).
developmental delay (8 papers, 2017 to 2025). "Haploinsufficiency of SOX5 causes Lamb–Shaffer syndrome, clinically characterized with developmental delay, speech delay, and behavioral disturbances." (PMID 36071901, 2022). "Similarly, a study using whole-exome sequencing technology found that a loss-of-function variant in SOX5 caused individuals to exhibit moderate developmental delay, mildly dysmorphic features, and scoliosis." (PMID 35739923, 2022).
hepatocellular carcinoma (8 papers, 2017 to 2025). A malignant tumor that arises from hepatocytes. "SOX5 encodes sex-determining region Y-box 5, and its overexpression is associated with the progression and distant metastasis of PC, nasopharyngeal carcinoma, and hepatocellular carcinoma." (PMID 29324665, 2018). "After a literature review, aberrant SOX5 expression was reported to play a critical role in the progression of various cancers, such as breast, lung, colorectal, melanoma, lymphoma, and hepatocellular carcinoma." (PMID 40274769, 2025). "Moreover, the miR-4516/SOX5 axis was involved in cell proliferation and invasion in human hepatocellular carcinoma." (PMID 38930863, 2024). "We aimed to explore the role of circ-SOX5 in the pathogenesis of hepatocellular carcinoma (HCC)." (PMID 35048790, 2022). "For example, SOX5 promoted EMT process by regulation of Twist1 in hepatocellular carcinoma." (PMID 28335789, 2017). "In hepatocellular carcinoma, SOX5 is up-regulated in hepatocellular carcinoma tissues and cell lines, and high levels of SOX5 can accelerate the migration and invasion of HCC cells in vitro." (PMID 38835366, 2024). "According to RNA sequencing, the host gene of hsa_circ_0098181 was sex determining region Y-box protein 5 (SOX5), a transcriptional factor whose roles in hepatocellular carcinoma and other liver diseases were not clear." (PMID 35264957, 2022).
lung adenocarcinoma (8 papers, 2018 to 2025). A carcinoma that arises from the lung and is characterized by the presence of malignant glandular epithelial cells. "It showed that SOX5 expression in lung adenocarcinoma was closely associated with clinical stages (r = 0.254, P < 0.05), and that SOX5expression in paracancerous tissues was correlated with tumor size (r = 0.211, P < 0.05)." (PMID 29541384, 2018). "Our findings suggest that SOX5 promotes tumor metastasis and could be a novel diagnostic marker and potential therapeutic and prognostic target in lung adenocarcinoma." (PMID 29541384, 2018). "To validate SOX5 levels in lung adenocarcinoma (LAC), we analyzed its expression in five paired LAC tissues and a panel of cell lines." (PMID 40697663, 2025). "Tube formation was promoted in by human umbilical vein ECs co-cultured with SOX5-overexpressed A549 cells (a human lung adenocarcinoma cell line)." (PMID 40640841, 2025). "FOXA1 contributed to acquisition of chemoresistance in human lung adenocarcinoma via transactivation of SOX5." (PMID 35498155, 2022). "All of these observations indicate that SOX5 is over-expressed in lung adenocarcinoma and promotes tumor progression." (PMID 29541384, 2018). "We first analyzed SOX5 expression in four human lung adenocarcinoma (LAC) samples and a series of cell lines." (PMID 29541384, 2018). "Inhibiting SOX5 expression attenuated metastasis and progression in lung cancer cells, while over-expressing SOX5 accelerated lung adenocarcinoma progression and metastasis via EMT." (PMID 29541384, 2018). "Here, we used immunohistochemical analysis to reveal that SOX5 levels were increased in 90 lung adenocarcinoma patients." (PMID 29541384, 2018). "Moreover, SOX5 has been identified as a predictor of poor prognosis in lung adenocarcinoma, and SOX5 is known to promote lung adenocarcinoma progression and metastasis through EMT." (PMID 38561355, 2024). "used immunohistochemical analysis to find that SOX5 is overexpressed in lung adenocarcinoma, and overexpressed SOX5 can accelerate the progression and metastasis of lung adenocarcinoma through EMT, and is also correlated with clinical stage, poor prognosis and overall survival time of LAC patients." (PMID 38835366, 2024). "In this study, we demonstrated that SOX5 was over-expressed in lung adenocarcinoma." (PMID 29541384, 2018). "Inhibition of SOX5 can inhibit cell proliferation, migration and EMT process to reverse chemotherapy resistance of docetaxel-resistant lung adenocarcinoma cells." (PMID 38835366, 2024). "SOX5 is known to participate in EMT in different cancer types (i.e., breast, prostate, hepatocellular, lung adenocarcinoma and osteosarcoma)." (PMID 35631574, 2022). "The high SOX5 expression in lung adenocarcinoma and non-tumor counterparts correlated with the patients’ poor prognosis." (PMID 29541384, 2018). "Our results indicate SOX5 promotes lung adenocarcinoma tumorigenicity and can be a novel diagnosis and prognosis marker of the disease." (PMID 29541384, 2018). "In addition, through the analysis of 90 clinical lung adenocarcinoma samples, it was found that VEGF expression was positively correlated with SOX5 expression, and the overexpression of SOX5 led to the activation of STAT3, which would increase the expression of VEGF and stimulate angiogenesis." (PMID 38835366, 2024). "In addition, SOX5 has been discussed as a resistance factor in docetaxel-resistant lung adenocarcinoma cells, where SOX5 plays a key role in exacerbating the development of EMT, metastasis, and chemotherapy resistance in docetaxel-resistant lung adenocarcinoma cells." (PMID 38835366, 2024).
melanoma (8 papers, 2016 to 2025). A malignant, usually aggressive tumor composed of atypical, neoplastic melanocytes. "Based on TCGA data, we found that SLNCR1 expression was positively associated with SOX5 expression in melanoma (R = 0.54, p < 0.01)." (PMID 38561355, 2024). "In contrast, survival analysis of melanoma patients with predominantly metastatic disease revealed that low SOX5 levels were associated with a poor prognosis." (PMID 26927636, 2016). "We observed a higher SOX5 expression in metastatic melanoma compared to primary melanoma, although the survival analysis revealed that very low SOX5 expression is associated with poor prognosis." (PMID 26927636, 2016). "Moreover, SOX5 has been shown to be associated with regulation by microphthalmia transcription factor (MITF) in melanoma." (PMID 38561355, 2024). "In summary, higher SOX5 expression was associated with a better clinical course of melanoma patients; we thus further studied the clinical relevance of SOX5 expression investigating the Breslow thickness of primary melanoma tumors." (PMID 26927636, 2016). "Overexpression of SOX5 reversed the inhibition of proliferation and migration of melanoma cells induced by SLNCR1 silencing." (PMID 38561355, 2024). "To further investigate the role of SOX5 in melanoma, we measured SOX5 expression levels in the 27 pairs of melanoma tissues and cells." (PMID 38561355, 2024). "We then overexpressed SOX5 in SLNCR1-silenced melanoma cells to determine its effects on cell proliferation, migration, and EMT markers." (PMID 38561355, 2024). "Supporting the results from the melanoma cell lines, we found increased expression of SOX9 and loss of expression of SOX2, SOX5, and SOX8, suggesting that SOX10KO cells reverted to a pre-NC state." (PMID 36040798, 2022). "This mode of Sox5 and Sox10 interaction has been reported in mouse melanocytes and in human melanoma cells, suggesting that an antagonistic interaction between Sox5 and Sox10 is widely conserved among vertebrates." (PMID 29621239, 2018). "A decreased proliferation rate was observed in all SOX5 siRNA transfected melanoma cells, except for one cell line (cell line A375)." (PMID 26927636, 2016). "In all three tested melanoma cell lines (MaMel-61e, MaMel-122 and MaMel-86b) the knockdown of SOX5 resulted in significantly increased MITF levels compared to cells transfected with control siRNA." (PMID 26927636, 2016). "We found low SOX5 expression to be an indicator for shorter survival of patients with melanoma tumors." (PMID 26927636, 2016). "Regarding clinical samples, SOX5 expression was distinctively up-regulated in metastatic compared to primary melanoma." (PMID 26927636, 2016). "We confirmed experimentally that SOX5 and SOX10 have an effect on MITF expression levels in melanoma cell lines; SOX5 down-regulation increases MITF expression, hinting at an inhibitory effect, while vice versa, SOX10 down-regulation led to MITF up-regulation." (PMID 26927636, 2016). "Strikingly, we obtained very good prediction results (PCC r = 0.76) by using the optimization parameters of the SOX5/SOX10 model learned on the NCI-60 data for the prediction of MITF levels of the independent melanoma data set (33 melanoma samples)." (PMID 26927636, 2016). "To analyze the effects of SOX5 knockdown on viability and invasion we transfected five melanoma cell lines with SOX5 siRNA or control siRNA pools." (PMID 26927636, 2016). "We observed a similar effect in human melanoma cells: A double knockdown of SOX5 and SOX10 partially rescued MITF expression compared to a single knockdown of SOX10." (PMID 26927636, 2016). "Additionally, we employed bioinformatic predictive analysis, combined with dual-luciferase reporter analysis and functional rescue assays, to elucidate the mechanistic target of the SLNCR1/SOX5 axis in melanoma." (PMID 38561355, 2024). "SOX5 was highly expressed in melanoma tissues and cell lines compared to controls." (PMID 38561355, 2024).
melanoma (continued). "Our findings showed that the knockdown of SLNCR1 resulted in the suppression of Ki67 and Vimentin expressions, suggesting that SLNCR1/SOX5 axis may promote melanoma growth in vivo via the regulation of the EMT pathway." (PMID 38561355, 2024). "SOX5 expression was significantly increased in melanoma tissues compared to normal tissues." (PMID 38561355, 2024). "Furthermore, results of GEPIA analysis showed that ACTB, SLC1A5, VASP, BRBB3, GAS7, ARTN2, and SOX5 were significantly increased in melanoma tissues (p < 0.05)." (PMID 38561355, 2024). "Additionally, we found that SOX5 knockdown led to MITF up-regulation in melanoma cells, while double knockdown with SOX10 showed a rescue effect; both effects were validated by reporter assays." (PMID 26927636, 2016). "Taken together, SOX5, SOX10 and MITF seem to have a crucial clinical impact and our developed linear regression based expression signature of these three genes associated in particular with melanomas with a small Breslow thickness." (PMID 26927636, 2016). "Besides SOX10, we identified SOX5 regulating MITF in human melanoma cells and validated its inhibitory effect experimentally by functional and reporter assays." (PMID 26927636, 2016). "Cells of a potential subset of melanoma, which is indicated by the bimodal distribution, may use the up-regulation of SOX5 to repress MITF in order to prevent its inhibitory effect on proliferation." (PMID 26927636, 2016). "Interestingly, we identified a bimodal distribution of SOX5 expression in tumor samples and also in the melanoma cell lines." (PMID 26927636, 2016). "Furthermore, SOX5 expression was significantly decreased after SLNCR1 knockdown in melanoma cells, indicating that SOX5 may be a downstream target molecule of SLNCR1." (PMID 38561355, 2024). "In addition to this, we found SOX5 to be a novel regulator of MITF in human melanoma cells." (PMID 26927636, 2016). "Within the SOX gene family, SOX4, SOX5, SOX9 and SOX10 are established key regulators in melanoma cells establishment and function." (PMID 40866912, 2025). "Mechanistically, we discovered that SLNCR1 promotes EMT of human melanoma by targeting SOX5, as downregulation of SLNCR1 expression leads to a decrease in SOX5 protein levels and inhibits melanoma tumorigenesis." (PMID 38561355, 2024). "SOX5 expression was significantly associated with N stage (p = 0.016), age (p = 0.046), tumor tissue site (p = 0.005), Breslow depth (p = 0.021), DSS event (p = 0.04), and PFI event (p = 0.004), indicating that SOX5 may participate in the occurrence and development of melanoma." (PMID 38561355, 2024). "In comparison, the SOX10+MITF– NCSC-like melanoma cell lines had acquired expression of other NC-derived lineage markers such as SOX2 (expressed in glial lineages), SOX5, and SOX8 (expressed in neural progenitors)." (PMID 36040798, 2022). "SOX5 has a strong inhibitory effect on MITF expression and seems to have a decisive clinical impact on melanoma during tumor progression." (PMID 26927636, 2016). "MITF regulation by SOX5 has only been shown in murine cells so far and hence we were interested in the regulatory effect of SOX5 on MITF in human melanoma cells and tumors, and its regulatory effect in combination with SOX10." (PMID 26927636, 2016). "In conclusion, our study revealed that SLNCR1 promotes EMT of melanoma by targeting SOX5, these findings suggest that SLNCR1 may serve as a potential marker for assessing the incidence and prognosis of melanoma." (PMID 38561355, 2024). "In summary, we could confirm our computational predictions, i.e. SOX5 is inducing and SOX10 is repressing MITF expression in the observed melanoma cells." (PMID 26927636, 2016). "Furthermore, we wanted to confirm computationally that SOX5 and SOX10 are regulators of MITF expression in melanoma cells and thus analyzed a dataset of melanoma cells only." (PMID 26927636, 2016).
melanoma (continued). "Interestingly, the prediction of Breslow thickness using all of the investigated regulators (SOX5, SOX10, and MITF) showed good prediction performance only for thin melanoma tumors (<1 mm) and was rather poor for thick melanomas." (PMID 26927636, 2016). "Interestingly, also SOX5 (p = 0.0008) and SOX10 (p = 3E-6) showed a significantly higher expression in melanoma samples compared to all other cells." (PMID 26927636, 2016). "Using our established regression model (MILP model) and the defined activity, we found the transcription factors SOX5 and SOX10 with which the model could predict best the gene expression values of MITF in various melanoma cell lines." (PMID 26927636, 2016). "Furthermore, hierarchical cluster analysis (average linkage and Euclidean distance) showed that SOX5 and SOX10 expression is sufficient to clearly distinguish melanoma from other cancer types." (PMID 26927636, 2016). "Thus, we performed functional assays to validate our in silico predictions in human melanoma cells and investigated the expression signatures of MITF, SOX5 and SOX10 in respect to clinically relevant parameters." (PMID 26927636, 2016). "Furthermore, SOX5 silencing suppressed the proliferation and migration capability of melanoma cells, but not invasion." (PMID 38561355, 2024). "MITF regulation by SOX5 has been shown only in murine cells, but not yet in human melanoma cells." (PMID 26927636, 2016).
gastric cancer (7 papers, 2021 to 2025). A primary or metastatic malignant neoplasm involving the stomach. "miR-338–3p acts as a tumor suppressor in gastric cancer, inhibiting cell growth, survival, and proliferation by directly targeting SOX5 and blocking Wnt/β-catenin signaling, while inducing apoptosis." (PMID 38835366, 2024). "Knockdown of circLDLRAD3 regulated the invasion and proliferation of gastric cancer cells through miR-588/SOX5, reducing cisplatin resistance in gastric cancer cells." (PMID 39314750, 2024). "Studies have found that the high expression of SOX5 in gastric cancer can increase the resistance of cancer cells to cisplatin, while inhibiting the expression of SOX5 can alleviate or reverse the resistance to cisplatin." (PMID 38835366, 2024). "In gastric cancer, it was also found that the expression level of SOX5 was significantly correlated with T stage, pTNM stage and lymph node metastasis." (PMID 38835366, 2024). "In addition, SOX5 also plays an abnormally high expression role as an oncogene in many other cancers (such as gastric cancer, lung cancer, ovarian cancer and colorectal cancer, etc.), thus regulating the occurrence, development and pathological process of cancer." (PMID 38835366, 2024). "In general, the expression of the SOX gene family is frequently down-regulated in gastric cancer and HCC, while studies focusing particularly on the SOX5 gene reported up-regulation in HCC tissues and cell lines as well as in gastric cancer." (PMID 34442866, 2021). "Study showed that overexpression of AFP in gastric cancer patients significantly inhibited the infiltration of CD8+T cell, could promote liver metastasis by regulating the PTEN/AKT1/SOX5/CES1 signaling axis." (PMID 40900791, 2025).